IGHV1OR21-1 (immunoglobulin heavy variable 1/OR21-1 (non-functional))
Synonyms: IGHV1/OR21-1
Gene: Immunoglobulin variable (V) gene on chromosome 21 (10,649,400 to 10,649,835, reverse strand). Ensembl gene ENSG00000277282.
Gene Ontology:
Molecular function: antigen binding
Biological process: immunoglobulin mediated immune response
Cellular component: extracellular region; plasma membrane
Homologues: Orthologues: mouse Ighv1-50 (65% identical), mouse Ighv1-74 (65% identical), mouse Ighv1-64 (64% identical), mouse Ighv1-69 (64% identical), mouse Ighv1-52 (63% identical), mouse Ighv1-53 (63% identical), mouse Ighv1-4 (62% identical), mouse Ighv1-55 (62% identical), mouse Ighv1-59 (62% identical), mouse Ighv1-61 (62% identical), mouse Ighv1-7 (62% identical), mouse Ighv1-85 (62% identical), and 47 more. Paralogues in human: IGHV1OR15-9 (91% identical), IGHV1-3 (79% identical), IGHV1-46 (79% identical), IGHV1-2 (77% identical), IGHV1OR15-1 (76% identical), IGHV1-45 (74% identical), IGHV1-18 (74% identical), IGHV1-24 (73% identical), IGHV1-69 (73% identical), IGHV1-69D (73% identical), IGHV1-69-2 (72% identical), IGHV1-58 (71% identical), and 65 more.